CTSL (cathepsin L)
Diseases named in the same sentence as CTSL in open-access papers (continued):
Sharing a sentence is not in itself a finding about the gene and the disease.
Obesity (10 papers, 2012 to 2025). Accumulation of substantial excess body fat. "Cathepsin L and some other cathepsins have been implicated in the development of obesity in humans and mice." (PMID 31771567, 2019). "Our cross-sectional results regarding CTSL and microbes may be interesting as Bifidobacterium has been associated with obesity and weight loss in animals and humans." (PMID 33042834, 2020). "We recently demonstrated that high‐fat‐diet‐induced obesity impairs the activity of cathepsin L (CTSL), a major lysosomal enzyme in mouse white adipose tissue, causing inflammatory responses and senescence." (PMID 33277792, 2021). "In this previous report, we demonstrated that alterations of CTSL maturation, followed by downregulation of CTSL enzymatic activity during the early development of obesity in WAT exacerbated autophagic clearance leading to autophagosome accumulation." (PMID 31959889, 2020). "Taken together, CTSL downregulation leads to complementary CTSB activation that can contribute to obesity-induced inflammation reactions in WAT." (PMID 31357643, 2019). "In particular, CTSK−/− and CTSL−/− mice are protected against diet induced obesity." (PMID 22844403, 2012). "However, since the impact of obesity on cathepsin L remains unclear, we are currently unable to explain the differences in expression between pure frailty and obese frailty." (PMID 39382189, 2024). "Thus, to explore whether there is a similar circuit to regulating fat storage in the mammal system, we should firstly demonstrate whether there is increased cathepsin L expression in some fat storage tissues among with diet-induced obesity." (PMID 31771567, 2019). "In this study, we identified, for example, the genes ENPP1, CTSL, CIDE-C, and ABHD12B as potential causal genes for obesity, and further validation (e.g., by qPCR in a large human population) and investigation of these genes might lead to biomarkers for obesity." (PMID 26482556, 2015). "In summary, although the exact causes and mechanisms are still unclear, lysosomal dysfunction represented by downregulated CTSL in WAT or adipocytes abrogates autophagy and can participate in obesity-related pathology." (PMID 31357643, 2019). "Thus, alterations of CTSL and CTSB expressions in WAT are very complicated, likely depending on the degree of obesity status, type of food, timing of tissue sampling, or animal species." (PMID 31357643, 2019). "Therefore, we focused on cathepsin abnormalities, especially CTSL, CTSB and CTSD, as a mechanism of obesity-related lysosomal dysfunction in WAT and liver." (PMID 31357643, 2019). "The obesity related phenotypes of CTSK−/− and CTSL−/− mice are also in agreement with this hypothesis." (PMID 22844403, 2012). "Our findings indicated that pure frailty increases cathepsin L expression, while obesity and obese frailty do not, suggesting pure frailty might elevate cathepsin L due to muscle atrophy or systemic inflammation." (PMID 39382189, 2024). "Furthermore, we detected several obesity candidate genes, for example, ENPP1, CTSL, and ABHD12B." (PMID 26482556, 2015).
pancreatitis (9 papers, 2013 to 2026). Inflammation of the pancreas. "A similar situation arose when trypsin activation and pancreatitis responses were studied in CTSL-deficient mice." (PMID 31235832, 2019). "In the zymogen fraction from Cst3−/− animals we observed significantly increased activities of CTSB and CTSL during pancreatitis, in comparison to control animals." (PMID 39962054, 2025). "Activation of CTSB and inhibition of CTSL appear to allow for efficient trypsinogen activation and the onset of pancreatitis." (PMID 39962054, 2025). "Lysosomal dysfunction in pancreatitis is indicated by the findings that the maturation of cathepsin B and cathepsin L are reduced and that autophagosome formation is increased while lysosomal degradation is decreased." (PMID 33990205, 2021). "While cathepsin B efficiently cleaves trypsinogen to produce enhanced levels of active trypsin promoting pancreatitis, cathepsin L acts a regulatory brake, and keeps the activation process under control." (PMID 32041276, 2020). "Even though trypsin activation was markedly increased in these mice, pancreatitis was still ameliorated, in all likelihood due to other effects of CTSL-deletion on immune cells and cell death pathways." (PMID 31235832, 2019). "This notion is supported by publications showing that the severity of pancreatitis is reduced in cathepsin L-KO mice." (PMID 28386074, 2017). "Malfunctioning lysosomes in pancreatitis allow an imbalance between these two cathepsins, resulting in less cathepsin L and accumulation of active trypsin." (PMID 24474939, 2013). "Therapeutic strategies aimed at restoring the CTSB–CTSL balance or promoting CTSL maturation may help mitigate pathological trypsin activation and reduce pancreatitis severity." (PMID 41530118, 2026). "In pancreatitis, heparanase is expressed by pancreatic acinar cells and infiltrated cells or possibly centroacinar cells, in which heparanase partially co-localizes with cathepsin L (overlay, yellow)." (PMID 28386074, 2017). "This indicates that cathepsin L may be involved in additional pathways which contribute to pancreatitis." (PMID 24474939, 2013). "Since cathepsin B converts trypsinogen to trypsin while cathepsin L digests both trypsinogen and trypsin, the imbalance between cathepsin B and cathepsin L, especially insufficient cathepsin L maturation, may contribute to trypsin accumulation and development of pancreatitis." (PMID 33990205, 2021). "Animal data as well as investigations of human samples suggest that, during pancreatitis, the lysosomal cysteine protease inhibitor CST3 undergoes redistribution into the zymogen-containing secretory compartment together with CTSB and CTSL." (PMID 39962054, 2025). "CTSB, CTSL, and CTSS are known to be up-regulated in pancreatitis, and although the roles of CTSB and CTSL are well-established that of CTSS is less known." (PMID 35183119, 2022). "To find out in which subcellular compartment this increased activity was located we prepared subcellular fractions of pancreatic tissue from control and 1 h pancreatitis animals and measured enzyme activities of CTSB, CTSL, trypsin, and chymotrypsin in these subcellular fractions." (PMID 39962054, 2025). "Taken together these findings suggest processing of CST3 in the zymogen granule fraction during pancreatitis which affects its inhibitory capacity for CTSB but not for CTSL." (PMID 39962054, 2025). "Interestingly, we did not observe this pH effect on CTSL activity after induction of pancreatitis in wild-type mice." (PMID 39962054, 2025).
rheumatoid arthritis (9 papers, 2011 to 2023). A chronic, systemic autoimmune disorder characterized by inflammation in the synovial membranes and articular surfaces. "The cathepsins including CTSL is known to be expressed at high levels in the joints of rheumatoid arthritis." (PMID 36911677, 2023). "Increased CTSL-mediated C3 activation, on the other hand, drives Th1 hyper-activity in rheumatoid arthritis and in systemic lupus erythematosus." (PMID 30405635, 2018). "A specific ribozyme of CTSL exhibited a similar reduction in the severity of destructive rheumatoid arthritis thereby confirming the involvement of this protease in collagen and proteoglycan degradation." (PMID 21687683, 2011). "Increased cathepsin L activity has been found to promote disease pathogenesis by creating an inflammatory environment associated with degradation of the ECM in cardiovascular disease, cancer, and rheumatoid arthritis." (PMID 27416066, 2016). "The DEGs which contributed to the pathway term “Rheumatoid arthritis” were CXCL8 (C-X-C Motif Chemokine Ligand 8), CTSL (Cathepsin L), CXCL2 (C-X-C Motif Chemokine Ligand 2), and CCL2 (C-C Motif Chemokine Ligand 2)." (PMID 36911677, 2023). "Cathepsin L (CTSL) is involved in the development of diseases such as myofibril necrosis in myopathy and ischemic myocardial disease, rheumatoid arthritis, renal tubular reactions in the course of proteinuria and in osteoporosis." (PMID 31052424, 2019).
prostate carcinoma (8 papers, 2013 to 2022). A carcinoma that arises from epithelial cells of the prostate gland. "Considering TMPRSS2 is mainly expressed in prostate cancer, we conclude that CTSL mutations primarily correlated with FURIN expression, which might further regulate SARS-CoV-2 entry in cancers." (PMID 35414771, 2022). "Studies on prostate cancer cell lines suggested that CTSL was associated with the motility of prostate tumor cells and therefore might be involved in tumor metastasis." (PMID 24289299, 2013). "In prostate cancer, the different CUX1 variants even seem to mediate antagonistic effects depending on cathepsin L activity: In androgen-sensitive tumors, cathepsin L is highly expressed and cleaves CUX1 into the tumor-promoting p110 isoform." (PMID 34070180, 2021). "Correlations between changes in tumor proliferation rate and expression of CTSL and other biomarkers in prostate cancer patients participating in a randomized controlled weight loss trial." (PMID 33042834, 2020). "In this study, we assessed EpCAM and CTSL levels with ELISA in prostate cancer tissues and determined the effect of epithelium content on tissue protein quantitation." (PMID 24289299, 2013). "m62A inhibited CTSL protein levels in a dose dependent manner in the prostate cancer cell line PC3." (PMID 35414771, 2022). "Our previous presurgical weight loss trial among 40 prostate cancer patients found that rapid (but not slow) weight loss resulted in increased tumor Ki67 and Cathepsin L (CTSL) gene expression." (PMID 33042834, 2020). "Besides having activity on cysteine proteases from C. maculatus digestive tract, AaCI-2S inhibited papain, bromelain, ficin, and cathepsin L and impaired cell proliferation in gastric and prostate cancer cell lines." (PMID 33266031, 2020). "After transducing the human Panc-1 tumor cell line with full-length p200 CUX1, we could verify by Western blot analysis that p200 CUX1 is—at least in part—processed into the p110 variant, most likely via proteolytic cleavage by cathepsin L in breast and prostate cancer." (PMID 34070180, 2021). "Our laboratory has previously shown that cathepsin L inhibition with KGP94 reduces invasion of breast and prostate cancer cells." (PMID 31565189, 2019).
SARS-CoV infection (8 papers, 2019 to 2025). "Previously, CTSL has been found to play pivotal roles in SARS-CoV infection by cleaving AYT| MSL motif within S proteins, which resulted in the activation of S proteins." (PMID 35572668, 2022). "Antiviral small molecules that inhibited cathepsin L were able to inhibit SARS-CoV infections in vitro and that of other viruses that depend on cathepsin L for entry, such as Ebola, Hendra, and Nipah viruses." (PMID 32143502, 2020). "CTSS has been observed to play a modest role in SARS-CoV infection, and may partially substitute for cathepsin L in certain cells." (PMID 40362649, 2025). "In cell culture experiments, the approved glycopeptide antibiotics (teicoplanin, telavancin, dalbavancin, and oritavancin) proved to be potent inhibitors of cathepsin L and were proved to prevent SARS-CoV infection in a dose-dependent manner within therapeutic dosage." (PMID 32668803, 2020). "In summary, our data reveal that CTSL is required for both SARS-CoV-2 and SARS-CoV infection and demonstrate the therapeutic potential of teicoplanin for universal anti-CoVs intervention." (PMID 35572668, 2022). "SARS-CoV infection was blocked by specific inhibitors of the pH-sensitive endosomal protease cathepsin L. S-mediated entry into Vero E6 and 293T/hACE2 cells was blocked by leupeptin, Z-lll-FMK (an inhibitor of both CTSB and CTSL), and E64c (an inhibitor of cysteine proteases)." (PMID 34239932, 2021). "Both compounds display a pronounced inhibitory effect against SARS-CoV infection (fusion) in HEK293T cells (IC50 teicoplanin: 3.76 ± 1.1 μM; dalbavancin; 9.64 ± 1.3 μM) but not against free cathepsin L enzyme (IC50 > 200 μM)." (PMID 32668803, 2020).
colon carcinoma (7 papers, 2020 to 2025). "Up to date, CTSL levels could be of diagnostic significance in colon cancer." (PMID 37537587, 2023). "Remarkably, in colon cancer cells, a role for nuclear CtsL in cell proliferation and cell cycle progression was reported." (PMID 39851495, 2025). "CTSL up-regulation has been widely identified and correlated with metastatic aggressiveness and poor patient prognosis of colon cancer." (PMID 37537587, 2023). "Cathepsin L (CTSL), one of the human cathepsin proteases, has been shown to be overexpressed in various carcinomas including ovary, cervix, breast, and colon tumors." (PMID 35284334, 2021). "Previous studies have demonstrated that CTSL is involved in a wide range of human malignancies, including ovarian, breast, prostate, lung, pancreatic, and colon cancers." (PMID 32388635, 2020). "The authors further confirmed the nuclear role of CtsL, showing, both by Western blotting and confocal microscopy, that it specifically accumulated in the nuclei of colon cancer cells during the G1/G0 phase and that it accumulated in the lysosomal compartment during the S and G2/M phases." (PMID 39851495, 2025). "It has been shown that intracellular C3 in human colon carcinoma Caco2 cells can cleave cathepsin L and B and release C3a, just like CTSL can cleave C3 in CD4+ T cells in a non-C3 convertase manner, and C3a secretion can be downregulated by treatment with cathepsin L and B inhibitors in these cells." (PMID 36969185, 2023). "IHC in 20 clinical specimens of colon and rectal cancer also verified the expressions of HMGB1 and CTSL were higher in colon cancer than in paracancerous tissues, raising the necessity to determine the changes associated with HMGB1-mediated CTSL and autophagy-lysosome pathway." (PMID 37537587, 2023). "In addition, cleavage of p53BP1 by CTSL contributes to genomic instability in triple negative breast cancer cells, and a role for nuclear CTSL was demonstrated for cell cycle progression in a colon cancer cell line." (PMID 35203107, 2022). "Nevertheless, the detailed molecular mechanism of HMGB1-mediated CTSL-lysosome function in colon cancer therapy and platinum drugs has not been clearly defined." (PMID 37537587, 2023).
myocardial infarction (7 papers, 2013 to 2025). Gross necrosis of the myocardium, as a result of interruption of the blood supply to the area, as in coronary thrombosis. "Knock-out mice deficient in cathepsin L have shown increased mortality in the course of myocardial infarction." (PMID 31247004, 2019). "Research on myocardial infarction searched C-reactive protein, myoglobin, myeloperoxidase, creatine phosphokinase, creatin kinase MB, cardiac troponin T and cathepsin-L, all reporting statistically significant result." (PMID 32040469, 2020). "Another study found higher cathepsin L in individuals who had acute and previous myocardial infarction or stable and unstable angina pectoris compared to controls, and that cathepsin L correlated moderately with the number of stenotic lesions." (PMID 29149174, 2017). "In a model of myocardial infarction, it has been shown that the expression of stem cell factor and stromal cell-derived factor-1 were significantly decreased in the myocardium of CTSL KO mice." (PMID 23585893, 2013).
thyroid cancer (7 papers, 2018 to 2023). "INSL3 was also demonstrated to promote early tumor cell invasiveness in human thyroid carcinoma cells by enhancing their metabolic activity and elastin-degrading potential via increasing the production of the lysosomal enzymes cathepsin-L and cathepsin-D." (PMID 34211824, 2021). "INSL3 could promote tumor growth and angiogenesis in nude mice model of thyroid cancer in a manner that appeared to be related to the action of RXFP2 and the secretion of S100A4 and (pro-) cathepsin-L." (PMID 35178089, 2022).
diabetic nephropathy (6 papers, 2017 to 2025). "CTSL-mediated degradation of proteins essential for normal podocyte architecture can result in proteinuria and renal failure and accompanies diabetic nephropathy." (PMID 40980878, 2025). "In diabetic nephropathy, cathepsin L-mediated activation of pro-heparanase into activated heparanase is associated with albuminuria and preceded the loss of synaptopodin in a streptozotocin-induced diabetes mouse model." (PMID 28491286, 2017). "This suggests that heparanase is continuously activated by immunocyte derived cathepsin L despite treatment with sepiapterin, which could potentially explain that restoration of glycocalyx coverage by sepiapterin in diabetic nephropathy was only partial." (PMID 28103268, 2017). "While sepiapterin successfully increased the modulating potential of NO in this model of diabetic nephropathy, immunocytes were not affected, hence glomerular heparanase and cathepsin L were not reduced and glycocalyx properties not restored." (PMID 28103268, 2017). "Moreover, CtsL activity also contributes to experimental diabetic nephropathy, as Ctsl−/− mice showed no detectable Hpse1, reduced renal macrophage infiltration and no albuminuria." (PMID 40899692, 2025). "A study of traditional Chinese medicine for the treatment of diabetic nephropathy revealed that ginsenoside Rh2 could ultimately alleviate diabetic nephropathy by inhibiting LMP, reducing the expression of CTSB and cathepsin L, and inhibiting caspase-1-mediated pyroptosis." (PMID 40129990, 2025). "Notably, the levels of CTSL mRNA expression were increased in patients with focal segmental glomerulosclerosis (FSGS) and in patients with diabetic nephropathy, but not in patients with MCD." (PMID 30350425, 2019).
fasciolosis (6 papers, 2013 to 2025). "The recombinant cathepsin L1 test uses recombinant pro-cathepsin L1 and targets antibodies against cathepsin, a cysteine protease, to diagnose fasciolosis caused by F. hepatica." (PMID 37736397, 2023). "Recently, native cathepsin-L cysteine proteinase was purified from the excretory secretory products of Fasciola and applied for sero-diagnosis of Fasciola infection in buffaloes using Dot-ELISA." (PMID 25568708, 2014). "Previous studies in our laboratory have shown the potential of F.hepatica cathepsin L1 antigen to detect Fascioliasis with high confidence." (PMID 24069474, 2013). "Using a panel of serum from Fasciola hepatica-infected patients, we have optimized an enzyme-linked immunosorbent assay (ELISA) which employs a recombinant form of the major F. hepatica cathepsin L1 as the antigen for the diagnosis of human fascioliasis." (PMID 24069474, 2013). "Therefore, this study aimed to design and investigate the immune response of multi-epitope Cathepsin L (MeCatL) driven short peptide vaccine for fasciolosis using immunoinformatic tools." (PMID 40475029, 2025). "The recombinant cathepsin L1 test utilizes recombinant pro-cathepsin L1 and targets antibodies against cathepsin, a cysteine protease, for diagnosing fasciolosis caused by F. hepatica, with no reported cross-reactions." (PMID 38534120, 2024). "Using a panel of serum from Fasciola hepatica-infected patients and from uninfected controls we have optimized an enzyme-linked immunosorbent assay (ELISA) which employs a recombinant form of the major F. hepatica cathepsin L1 as the antigen for the diagnosis of human fascioliasis." (PMID 24069474, 2013).